PIK3CA (phosphatidylinositol-4,5-bisphosphate 3-kinase catalytic subunit alpha)
Diseases named in the same sentence as PIK3CA in open-access papers (continued):
Sharing a sentence is not in itself a finding about the gene and the disease.
tumor (continued). "Regarding tumor tissue‐based subgroups, the 6‐month PFS rate was highest (62.5%; one‐sided CI 28.92‐100) in the PIK3CA‐mutated subgroup (N = 8) and lowest (0%; one‐sided CI 0.0‐100) in the PTEN loss subgroup (N = 2)." (PMID 32352244, 2020). "Paired tumor-normal tissues from 35 PIK3CA-mutant dMMR patients were subjected to the hybrid capture-based NGS testing to parallelly profile somatic mutations of 33 cancer-related genes, MSI status and germline mutations." (PMID 32328187, 2020). "Protein staining for biomarkers related to EC (CECR1, KIF26B, PIK3CA) was mainly localized to the cytoplasm of tumor cells." (PMID 32133296, 2020). "For the 45 primary tumour samples screened in the TAMRAD study, the number of patients with a PIK3CA mutation was too small for relevant statistical analysis." (PMID 32566979, 2020). "A PPA of 71.7% and an NPA of 100% for the detection of eligible PIK3CA alterations were observed as compared to the tumor tissue PCR CTA." (PMID 32976510, 2020). "The most established cell-free tumor DNA (ctDNA) factors associated with ET resistance [ESR1 and phosphatidylinositol-4,5-bisphosphate 3-kinase, catalytic subunit alpha (PIK3CA) mutations] were assessed through next-generation sequencing." (PMID 33072577, 2020). "In BELLE-2, 21% of patients who had PIK3CA-wild-type tumor tissue at randomization had evolved to PIK3CA-mutant status via ctDNA collected at a later time point, though the reference period is not reported." (PMID 32637176, 2020). "EMT and enriched CSC phenotypes were observed in the 4NQO‐induced tumor from the PIK3CA mice (hereafter referred to as the PIK3CA‐tumors) in comparison with the 4‐NQO‐induced tumors from the control mice (hereafter referred to as the control‐tumors)." (PMID 31600013, 2020). "Our data suggest promising anti-tumor efficacy of alpelisib alone or in combination with paclitaxel in PIK3CA-mutant GC cells." (PMID 32704014, 2020). "Addition of a PI3K inhibitor to the combination of BMP7v and chemotherapy-induced tumor regression of PIK3CA-mutant tumor xenograft, further supporting the potential clinical application of this combination therapy." (PMID 31591478, 2020). "In case of the hypermutating tumor, we identified the two most common KRAS and PIK3CA activating mutations." (PMID 32873813, 2020). "While these HPV-positive HNSCC cell lines mostly recapitulate the genomic landscape of HNSCC tumours, they do lack some of the common genetic abnormalities present in clinical HNSCC tumours, particularly PIK3CA activating mutations." (PMID 33322840, 2020). "Down-regulation of PTEN and PIK3CA gene activation is frequently observed in neoplasms, including OSCC." (PMID 33287350, 2020). "IBL-302 demonstrated single-agent, anti-tumour efficacy in suppression of pAKT, pmTOR and pBAD in the SKBR-3, BT-474 and HCC-1954 HER2+/PIK3CA-mutated cell lines." (PMID 32042115, 2020). "We showed the relationship between the number of copies of the PIK3CA gene and the grade of the tumor." (PMID 33287350, 2020).
tumor (continued). "The Eve/Exe combination remains a valid, and in many cases preferable (e.g., PIK3CA-wt neoplasms, or in diabetic or malnourished patients), treatment option for HR+ HER2− mBC patients undergoing disease progression on/after prior AI therapy." (PMID 32252811, 2020). "Single copies of mutant KRAS cooperate with mutant PIK3CA to induce tumor transformation in immortalized human epithelial cells." (PMID 31781501, 2019). "This group found copy numbers of clinically actionable genes (i.e., AR, BRCA2, PIK3CA) to be 88.9% concordant between cfDNA and tumour DNA." (PMID 31817150, 2019). "A multivariate Cox proportional hazards model was used to combine expression levels of PTEN, ARID4B, and PIK3CA with time to tumor recurrence from the dataset GSE4027228 into an integrated risk score model." (PMID 31551414, 2019). "Adoptive transfer of tumor antigen–experienced T cells eliminated Pik3ca-null tumors in immunodeficient mice." (PMID 31112530, 2019). "The resulting frequencies of some mutated genes such as NOTCH1 (33.3%), PIK3CA (25.6%), and KMT2D (30.8%) were higher compared to that in previously single-tumor studies." (PMID 30975989, 2019). "In an important paper from the Garraway lab, PIK3CA mutations or PTEN inactivation were shown to differentially correlate with AKT phosphorylation levels in a number of cancer cell lines and tumor samples." (PMID 30999672, 2019). "Activation of this pathway by mutations of the PIK3CA gene or loss of tumor suppressor phosphatase and tensin homolog (PTEN) protein expression promotes tumor growth and proliferation." (PMID 31227862, 2019). "They found an enrichment of tumours with HER2 amplification in cetuximab‐resistant KRAS/NRAS/BRAF/PIK3CA wild‐type tumours." (PMID 31282586, 2019). "The presence of mutations in the PI3K encoding gene (PIK3CA gene) and AKT gene, as well as the phosphorylation levels of AKT at Thr308 in Merkel cell carcinoma (MCC) tumor samples and cell lines were investigated." (PMID 31408949, 2019). "Other variants detected in this tumor, such as those inFGFR3,PDGFRA,KDR (c.1416A>T),CSF1R,EGFR,RET,HRAS,PIK3CA,FLT3 (c.1310-3T>C), andSMAD4, are benign." (PMID 32612806, 2019). "Based on our results, we believe that abrogating PIK3CA-AKT signaling in tumor cells attracts both CD4+ and CD8+ T cells to infiltrate the tumors." (PMID 31112530, 2019).
tumor (continued). "This would potentially allow PIK3CA activation to act as a continuous driver/facilitator of genetic changes in cancer, but also offer a druggable opportunity to interfere with tumour evolution." (PMID 31374965, 2019). "PIK3CA mutant/HER2pos tumours had lower pCR in the neoadjuvant setting compared with wild-type tumours." (PMID 31281421, 2019). "Among the most commonly altered of the regulatory genes that are involved in cellular metabolism were PIK3CA (in 32% of tumours), MYC (in 14%) and HIF1A (in 11%)." (PMID 31754644, 2019). "Optimized siRNAs targeting KRAS impaired colon cancer growth in vivo while combinatorial inhibition of KRAS and PIK3CA/PIK3CB significantly improved tumor control compared to single agents alone, demonstrating that targets can be effectively multiplexed." (PMID 31681559, 2019). "In order to identify possible mechanisms of resistance to anti-EGFR MoAbs in CRC, we analyzed tumor samples from 21 KRAS/NRAS/BRAF/PIK3CA wt mCRC patients enrolled in the CAPRI-GOIM clinical trial by targeted sequencing." (PMID 31226844, 2019). "Data from human tumor sequencing efforts have shown that KRAS and PIK3CA mutations can co-occur, but their co-occurrence depends upon the disease." (PMID 31652979, 2019). "Another limitation is that FFPE tumor tissue was only collected from 42% of the ITT population, and only 41% of these samples were tested for both PIK3CA amplification and mutation." (PMID 30867034, 2019). "The previous work on molecular mechanism of UCEC has indicated that PIK3CA played a crucial role in development of tumor." (PMID 31472672, 2019). "The patient’s primary tumor and the derived PDX had activating PIK3CA E545K and ERBB2 L755S mutations and we previously reported that this PDX is resistant to irinotecan alone." (PMID 31627299, 2019). "Pik3ca-null tumors contained significantly more tumor-infiltrating T cells than WT tumors, and the αKO tumors regressed only in mice with functional T cells." (PMID 31112530, 2019). "A single HPV (-), PIK3CA wild type human tumor was propagated and split into two cohorts of mice - vehicle control (n = 12) or BYL719 (n = 10)." (PMID 31235758, 2019). "We observed persistent mTORC1 signalling in BYL719-insensitive cells, which was consistent with the report that the activation status of mTORC1 is a determinant of drug sensitivity of PIK3CA mutant tumours." (PMID 31889900, 2019). "Together with CDH1, PIK3CA and ERRB2 were the most common mutated genes in this series and showed mutations in 9 (33%) and 7 (26%) tumours respectively." (PMID 30641862, 2019). "MSI tumours are characterised by MutL homologue 1 (MLH1) silencing and a high mutation burden in genes as PIK3CA and receptor tyrosine protein kinase (ERBB3/HER3)." (PMID 31235864, 2019). "Another study revealed that patients with PIK3CA E545K gene mutations were in a more advanced disease, T stage III or IV and had tumor recurrence." (PMID 32099598, 2019). "Beyond the demonstration of strong potential for driving tumor development in the preclinical setting, PIK3CA p.H1047R has shown sensitivity to the mTOR inhibitor everolimus." (PMID 31197119, 2019). "The presence of circulating free tumour DNA for the mutations BRAF, K-ras, N-ras, and PIK3CA mutations has been used to identify patients with MRD and also as a marker for the resistance to EGFR therapy, such as cetuximab or panitumumab." (PMID 31281432, 2019). "For examples, while p110α is predominantly required for growth of tumours driven by RTKs, mutant RAS, and/or PIK3CA mutations, p110β is the dominant isoform in PTEN-deficient tumours." (PMID 35582276, 2019). "Preclinically, neratinib inhibited proliferation in HER2-amplified, PIK3CA-mutant tumor cell lines, and inhibited tumor growth in a HER2-positive, PIK3CA-mutant patient-derived xenograft model." (PMID 31141894, 2019).
tumor (continued). "In conclusion, our results indicate that APOBEC3B mRNA is similarly upregulated in DCIS and IBC, but declines in PIK3CA-mutated IBC, which suggests that APOBEC3B plays a role in the early stages of breast carcinogenesis." (PMID 31357602, 2019). "A major value-added of our study is the assessment of the relationship between RAS, PIK3CA, and BRAF tumor mutation status with clinical response to chemotherapy in the metastatic setting." (PMID 31036005, 2019). "Thirty-one tumors presented concomitant mutations in two genes; three tumors presented concomitant mutations in three genes including one tumor with BRAF, NRAS and PIK3CA concomitant mutations and two tumors with BRAF, KRAS, and PIK3CA concomitant mutations." (PMID 31036005, 2019). "Prior to administration of HER2-targeted therapies, in 28.6% of the patients, HER2-amplified CTCs had PIK3CA mutations, known to be associated with resistance to anti-HER2 treatment and worse outcome of patients with HER2-positive tumours." (PMID 30691008, 2019). "Rapamycin was responded well in cancer cells harboring PIK3CA and/or PTEN mutations (P = 0.0123) in a preclinical study, and inhibited tumor volume and microvasculature growth when was applied in a mouse xenograft model." (PMID 30754640, 2019). "The re-biopsied tumour at resistance was PIK3CA wt but had low PIK3R1 expression and acquired an IRS1 P313S variant that was not present in the sensitive tumour." (PMID 31653970, 2019). "Loss of PIK3CA or inhibition of its effector AKT increased the expression of MHC class I and CD80 on tumor cells." (PMID 31112530, 2019). "Pre-clinically, neratinib has demonstrated potent anti-proliferative activity in HER2-amplified, PIK3CA-mutant tumor cell lines." (PMID 30867034, 2019). "This resulted in reduced tumour growth that was driven by the PIK3CA and HPV oncogenes in oral SCC (OSCC)." (PMID 30970654, 2019). "Among the intent-to-treat population (n = 2840), tumor specimens were available for PCR testing (991 patients) and PIK3CA FISH (702 patients)." (PMID 30867034, 2019). "In the subcutanous xenograft models, isogenic PIK3CA WT and mutant cells are implanted pair-wise into the same mouse, whereas in the othotopic models each mouse bears either a PIK3CA WT or a mutant tumor." (PMID 31844152, 2019). "Prespecified exploratory analyses in BELLE-2 showed that the combination regimen resulted in meaningful clinical benefits in the patients with circulating tumor DNA (ctDNA) PIK3CA mutant." (PMID 30782187, 2019). "A genetic landscape sequencing study on circulating tumor DNA of samples from the PALOMA-3 study demonstrated that acquired mutations in the RB1, PIK3CA, and ERα genes emerged in the treatment arm of fulvestrant and palbociclib." (PMID 31178825, 2019).
tumor (continued). "To investigate the mechanisms of PIK3CA mutation on CRC stem cells, we determined the PI3K/Akt signaling pathway activation and CSC markers in CRC tumor tissues by western blotting." (PMID 29970892, 2018). "Cancer cells with GA in PIK3CA have been shown to be more susceptible to isoform-specific inhibitors of the PI3K pathway (PI3Ki) in vitro, in vivo, and in patients than tumor cells with wild-type PIK3CA9–19." (PMID 30237504, 2018). "Characteristically, the recurrently mutated genes in CRC, with the exception of PIK3CA and SMAD4, show a low degree of discordance between the primary tumor and the synchronous liver metastasis, confirming their biological role as driver “trunk” mutations." (PMID 30282914, 2018). "The edited peptides showed abundances elevated beyond normal levels (“over-editing”) in 7% of all tumours, which is a prevalence comparable to the most frequent neoantigen epitopes like PIK3CA H1047R, which is expressed in 4% of all tumours." (PMID 30254248, 2018). "VISTA expression was present in 8.8% out of 464 analyzed samples, and was associated with clinical and molecular features such as Lauren phenotype, tumor localization, EBV infection, KRAS and PIK3CA mutational status and PD-L1 expression." (PMID 30008616, 2018). "PIK3CA mutation status and PTEN expression were evaluated in 24 formalin-fixed, paraffin-embedded tumor samples from parts 2A, 2B and 2C." (PMID 30185228, 2018). "Increased pAkt levels were observed in PIK3CA mutant tumor tissues comparing with those wild type tumors." (PMID 29970892, 2018). "In conclusion, our study demonstrates that ≥20% tumor cellularity is required to identify T790M mutation as the cause of TKI resistance, and to detect HER2/BRAF/PIK3CA mutations in biopsy samples using the amplification‐based NGS testing." (PMID 29518290, 2018). "Given the concordance between ddPCR in blood vs. tumor specimens, we next proceeded to evaluate the frequencies of ESR1 mutations and PIK3CA mutations in the entire cohort (n = 155)." (PMID 30083595, 2018). "In premenopausal women, patients with PIK3CA wild-type tumors had lower tumor grade, higher ER expression, and lower AR expression when compared to patients with PIK3CA mutant tumors (P = 0.041, P = 0.025, and P = 0.047, respectively)." (PMID 29707142, 2018).